CBY1 (chibby 1, beta catenin antagonist)
Description:
Inhibits the Wnt/Wingless pathway by binding to CTNNB1/beta-catenin and inhibiting beta-catenin-mediated transcriptional activation through competition with TCF/LEF transcription factors. Has also been shown to play a role in regulating the intracellular trafficking of polycystin-2/PKD2 and possibly of other intracellular proteins. Promotes adipocyte and cardiomyocyte differentiation (By similarity).
Synonyms: ARB1; C22orf2; CBY; PGEA1; PIGEA14; PIGEA-14; Chibby; Chibby1; HS508I15A
Tractability: PROTAC: its protein half-life has been measured.
Gene: Protein-coding gene on chromosome 22 (38,656,375 to 38,673,868, forward strand). Ensembl gene ENSG00000100211.
Subcellular location: Nucleus speckle; Cytoplasm, cytoskeleton, cilium basal body; Cytoplasm, cytoskeleton, microtubule organizing center, centrosome, centriole; Golgi apparatus; Golgi apparatus, trans- Golgi network; Cell projection, cilium, flagellum; Cytoplasm; Nucleus
Subcellular location (Human Protein Atlas): Centrosome; Nucleoli; Nucleoplasm
Pathways (Reactome):
Signal Transduction: Deactivation of the beta-catenin transactivating complex
Gene Ontology:
Molecular function: beta-catenin binding; identical protein binding; protein binding; protein homodimerization activity
Biological process: intracellular protein localization; negative regulation of DNA-templated transcription; negative regulation of Wnt signaling pathway; protein homotetramerization; cardiac muscle cell differentiation; fat cell differentiation
Cellular component: centriole; centrosome; cytoplasm; nuclear speck; nucleus; trans-Golgi network; cytosol; nucleoplasm; sperm flagellum; ciliary basal body; Golgi apparatus; motile cilium
Genetic constraint (gnomAD): Loss-of-function variants: 6 observed, 10.39 expected, observed/expected ratio (o/e) 0.58, 90% interval 0.31 to 1.14. The upper end of that interval is the gene's LOEUF score, 1.14, which puts it in group 4 of 6, group 1 being the genes least tolerant of losing a copy. Missense variants: 102 observed, 113.23 expected, observed/expected ratio (o/e) 0.9, 90% interval 0.77 to 1.06. Synonymous variants: 42 observed, 45.74 expected, observed/expected ratio (o/e) 0.92, 90% interval 0.72 to 1.19.
Homologues: Orthologues: chimpanzee CBY1 (100% identical), macaque CBY1 (99% identical), dog CBY1 (90% identical), guinea pig CBY1 (86% identical), mouse Cby1 (84% identical), zebrafish cby1 (74% identical), tropical clawed frog cby1 (71% identical). Paralogues in human: CBY3 (42% identical), CBY2 (29% identical), CCDC70 (13% identical).
Diseases named in the same sentence as CBY1 in open-access papers:
CBY1 is named in the same sentence as 31 diseases in open-access papers, as found by Europe PMC text mining. Sharing a sentence is not in itself a finding about the gene and the disease. The quoted sentences say what the papers report.
chronic myeloid leukemia (5 papers, 2013 to 2024). "The down-modulation of the β-catenin antagonist Chibby 1 (CBY1) associated with the BCR-ABL1 fusion gene of chronic myeloid leukemia (CML) contributes to the aberrant activation of β-catenin, particularly in leukemic stem cells (LSC) resistant to tyrosine kinase (TK) inhibitors." (PMID 26147002, 2015). "CBY1 is called chibby 1, previous studies have demonstrated that CBY1 is downregulated in HCC, chronic myeloid leukemia, and colon carcinoma." (PMID 33934099, 2021).
breast carcinoma (3 papers, 2021 to 2025). "In line with this, our data show that CBY1 is a tumor suppressor associated with good prognosis in breast cancer." (PMID 33934099, 2021). "Correspondingly, ectopic CBY1 significantly decreased SOX2, Nanog, and CD44, the representative breast cancer stemness marker expressions both in mRNA and protein levels, implying that CBY1 has the ability to inhibit the stemness of BCSCs." (PMID 33934099, 2021). "Stemness in breast cancer is maintained by the long non-coding RNA408 (Lnc408)—dependent recruitment of Sp3 to CBY1 gene promoters to inhibit expression of CBY1, which indirectly enhances levels of nuclear β-catenin and β-catenin regulated cancer stem cell-related genes." (PMID 36982239, 2023). "Indeed, the breast cancer patients with high level of CBY1 had a higher overall survival in comparison with these with low level of CBY1." (PMID 33934099, 2021). "The lnc408/CBY1 axis might provide new insights into the mechanism of BCSC’s self-renewal and theoretical support for finding new targets of breast cancer diagnosis and therapy." (PMID 33934099, 2021).
ciliopathy (3 papers, 2020 to 2024). A genetic disorder of the cellular cilia or the cilia anchoring structures, the basal bodies, or of ciliary function. "In accordance with the clinical and mutational findings in the affected individuals, we demonstrated that depletion of Cby1 in zebrafish causes ciliopathy‐related phenotypes." (PMID 33131181, 2020). "In addition, mutations and the downregulation of CBY1 have been associated with a variety of diseases such as ciliopathy characterized by Joubert syndrome, pancreatitis, and colon cancer." (PMID 39650190, 2024). "Our data show that CBY1 LOF‐variants cause a ciliopathy with features of Joubert syndrome." (PMID 33131181, 2020). "We also demonstrated that depletion of Cby1 in zebrafish causes ciliopathy‐related phenotypes." (PMID 33131181, 2020). "We demonstrated that CEP164 (also known as NPHP15), which is mutated in human ciliopathies including nephronophthisis and BBS23,24, directly interacts with and recruits Cby1 to the distal appendages during ciliogenesis." (PMID 34446743, 2021). "The Cby1-KO mouse model, therefore, provides a viable model to study the pancreatic condition of human ciliopathy patients." (PMID 34446743, 2021).
Joubert syndrome (3 papers, 2020 to 2024). Joubert syndrome (JS) is characterized by congenital malformation of the brainstem and agenesis or hypoplasia of the cerebellar vermis leading to an abnormal respiratory pattern, nystagmus, hypotonia, ataxia, and delay in achieving motor milestones. "We identified biallelic loss‐of‐function (LOF) variants in CBY1, segregating with the clinical features of Joubert syndrome in the families." (PMID 33131181, 2020).
colon cancer (2 papers, 2013 to 2024). "Accordingly, Cby1 enforced expression in colon cancer and CML cell lines promotes beta catenin nuclear export and transcriptional attenuation." (PMID 24339928, 2013). "Cby1 downmodulation has a role in the sustained activation of Wnt/beta catenin signaling in pediatric ependymomas and colon cancer cell lines." (PMID 24339928, 2013).
lipomatosis (2 papers, 2021 to 2025). A neoplastic process characterized by diffuse overgrowth of mature adipose tissue. "Shortly after birth, Cby1-KO pancreata show substantial exocrine degeneration, which progressively worsens into adulthood, leading to pancreatic atrophy with significant lipomatosis." (PMID 34446743, 2021). "Pancreatic abnormalities in adult Cby1-KO mice included disorganized acinar morphology, profound ductal dilation, mucus accumulation, and lipomatosis (Adult)." (PMID 34446743, 2021).
Bardet-Biedl syndrome (1 paper, 2017). A ciliopathy with multisystem involvement. "We further showed that CEP164, which is mutated in nephronophthisis and Bardet-Biedl syndrome (BBS), both of which are classified as ciliopathies, directly interacts with and recruits Cby1 to the distal appendage/transition fiber of the mother centriole/basal body during primary ciliogenesis." (PMID 29244804, 2017).
cholelithiasis (1 paper, 2025). The presence of crystallized deposits forming in the gallbladder or biliary tree, primarily composed of cholesterol, bilirubin, and bile. "The TWAS analysis showed that overexpression of SUN2, JOSD1, and CBY1 was negatively associated with the risk of cholelithiasis and GERD in the blood and esophagus-related tissues, while overexpression of JOSD1 and CBY1 was positively associated with these 2 diseases in the liver tissue." (PMID 40139907, 2025). "In general, we identified 3 putatively functional genes shared between cholelithiasis and GERD, including SUN2, CBY1, and JOSD1, overexpression of which was negatively associated with the risk of cholelithiasis and GERD in the esophagus-related tissues." (PMID 40139907, 2025).
chronic pancreatitis (1 paper, 2021). A chronic inflammatory process causing damage and fibrosis of the pancreatic parenchyma. "Taken together, our data suggest that ablation of Cby1 results in progressive loss of exocrine acinar cells concomitant with chronic pancreatitis, while overall endocrine architecture and function appear normal." (PMID 34446743, 2021). "To examine if Cby1-KO mice show any signs of chronic pancreatitis, we performed immunohistochemistry for inflammatory markers." (PMID 34446743, 2021). "Furthermore, trichrome staining to detect collagen deposition revealed extensive fibrosis in the Cby1-KO pancreas (arrows), consistent with chronic pancreatitis." (PMID 34446743, 2021).
colorectal cancer (1 paper, 2018). A primary or metastatic malignant neoplasm that affects the colon or rectum. "Also, in colorectal cancer cells, CBY1 knockdown has been shown to promote mesenchymal to epithelial transition." (PMID 29963229, 2018).
ependymoma (1 paper, 2013). A WHO grade II, slow growing tumor of children and young adults, usually located intraventricularly. "Indeed, Cby1 downmodulation either due to C22orf2 loss or promoter hypermethylation is the most frequent genetic lesion in cranial pediatric ependymomas." (PMID 24339928, 2013).
esophageal cancer (1 paper, 2025). A primary or metastatic malignant neoplasm involving the esophagus. "Prior research has reported the negative effect of CBY1 and SUN2 genes on tumorigenesis, which implied a potential role of them in the pathogenesis of gallstone disease and GERD, given that these 2 diseases are risk factors for gallbladder and esophageal cancer, respectively." (PMID 40139907, 2025).
melanoma (1 paper, 2018). A malignant, usually aggressive tumor composed of atypical, neoplastic melanocytes. "CBY1 prevents the transcriptional activity of beta-catenin, which alteration is a key element in radial growth phase of melanoma." (PMID 29963229, 2018). "Although it has not been investigated directly in melanoma cells, we can speculate a potential activity of CBY1 in this neoplasm." (PMID 29963229, 2018).
ovarian carcinoma (1 paper, 2024). A malignant neoplasm originating from the surface ovarian epithelium. "In summary, our research sheds light on CBY1 as a crucial nuclear target for MAP7 within cisplatin-resistant A2780-DDP ovarian cancer cells." (PMID 38726137, 2024). "This supports the hypothesis that MAP7's nuclear presence, particularly its interaction with CBY1, contributes significantly to the modulation of the Wnt/β-catenin pathway and the development of cisplatin resistance in ovarian cancer cells." (PMID 38726137, 2024).
cancer (5 papers, 2020 to 2026). A tumor composed of atypical neoplastic, often pleomorphic cells that invade other tissues. "Both external validation and IHC analysis consistently confirmed the associations of CBY1, CASP8, PLOD1, and several methylation sites (cg09907170, cg09395195, cg08129017, and cg14808739) with their corresponding cancers." (PMID 42052171, 2026). "Our study unveils, for the first time, the pairwise interactions among MAP7, β-catenin, and CBY1, shedding light on their dynamic equilibrium and signaling within cells and offering avenues for novel cancer treatment strategies targeting these interactions." (PMID 38726137, 2024). "CBY1, also known as β-cyclin antagonist, is a protein-coding gene that competes with transcription factors for binding to β-cyclin, a transcriptional activator and oncoprotein involved in the development of several cancers, to inhibit its mediated transcriptional activation." (PMID 39650190, 2024).
tumor (4 papers, 2012 to 2021). "Lastly, the effect of lnc408/CBY1 axis on tumorigenesis and tumor growth was assessed in vivo by injection of lnc408-knocked down BCSCs and lnc408-overexpressing non-BCSCs into female nude mice." (PMID 33934099, 2021). "Meanwhile, nuclear β-catenin protein, the downstream target of lnc408/CBY1 axis, was significantly increased in the tumor derived from injected BCSC (BCSC/shCtrl) compared to the tumor from injected non-BCSCs (non-BCSC/Vec), and it was reduced in tumor derived from lnc408-silenced BCSCs." (PMID 33934099, 2021). "Extensive search of the literature revealed a potential key role of genes at the identified porcine loci in tumor invasion (DST, PLEKHA5, CBY1, LIMK2 and ETV5) and immune response modulation (ETV5, HERC3 and DICER1) of the progression phenotypes." (PMID 29963229, 2018).
CBY1 also shares sentences with these, for which no sentence is quoted: pancreatitis (2 papers); Bacterial Infections (1); exocrine pancreatic insufficiency (1); frontometaphyseal dysplasia (1); infection (1); laryngeal squamous cell carcinoma (1); malnutrition (1); Meckel syndrome type 13 (1); Meckel syndrome, type 2 (1); osteofibrous dysplasia (1); otitis media (1); polydactyly (1); primary ciliary dyskinesia (1); prostate carcinoma (1); spondylometaphyseal dysplasia (1).